POLR1F (RNA polymerase I subunit F)
Description:
Component of RNA polymerase I (Pol I), a DNA-dependent RNA polymerase which synthesizes ribosomal RNA precursors using the four ribonucleoside triphosphates as substrates. Through its association with RRN3/TIF-IA may be involved in recruitment of Pol I to rDNA promoters.
Synonyms: TWISTNB; RPA43; A43
Tractability: Small molecule: a structure with a bound ligand is known.
Gene: Protein-coding gene on chromosome 7 (19,695,461 to 19,709,045, reverse strand). Ensembl gene ENSG00000105849.
Subcellular location: Nucleus, nucleolus
Subcellular location (Human Protein Atlas): Nucleoli fibrillar center; Nucleoplasm
Pathways (Reactome):
Gene expression (Transcription): B-WICH complex positively regulates rRNA expression; NoRC negatively regulates rRNA expression; RNA Polymerase I Promoter Escape; RNA Polymerase I Transcription Initiation; RNA Polymerase I Transcription Termination
Gene Ontology:
Biological process: transcription elongation by RNA polymerase I; nucleolar large rRNA transcription by RNA polymerase I; termination of RNA polymerase I transcription; transcription initiation at RNA polymerase I promoter; DNA-templated transcription; DNA-templated transcription initiation
Cellular component: fibrillar center; nucleoplasm; RNA polymerase I complex; nucleus; nucleolus
Genetic constraint (gnomAD): Loss-of-function variants: 25 observed, 25.67 expected, observed/expected ratio (o/e) 0.97, 90% interval 0.71 to 1.36. The upper end of that interval is the gene's LOEUF score, 1.36, which puts it in group 5 of 6, group 1 being the genes least tolerant of losing a copy. Missense variants: 435 observed, 426.76 expected, observed/expected ratio (o/e) 1.02, 90% interval 0.94 to 1.1. Synonymous variants: 162 observed, 159.22 expected, observed/expected ratio (o/e) 1.02, 90% interval 0.89 to 1.16.
Homologues: Orthologues: chimpanzee POLR1F (99% identical), macaque POLR1F (98% identical), dog POLR1F (81% identical), guinea pig POLR1F (81% identical), pig POLR1F (80% identical), mouse Polr1f (74% identical), rat Polr1f (73% identical), tropical clawed frog polr1f (45% identical), zebrafish polr1f (43% identical). Paralogues in human: POLR3H (14% identical), POLR2G (13% identical).
Diseases named in the same sentence as POLR1F in open-access papers:
POLR1F is named in the same sentence as 10 diseases in open-access papers, as found by Europe PMC text mining. Sharing a sentence is not in itself a finding about the gene and the disease. The quoted sentences say what the papers report.
viral infection (1 paper, 2024). "UBL5 (ubiquitin-like protein 5), SNIP1 (Smad Nuclear Interacting Protein 1), TWISTNB (RNA Polymerase I Subunit F) and MFAP1 (Microfibril Associated Protein 1) have not been reported in affecting viral infection before." (PMID 39715740, 2024).
POLR1F also shares sentences with these, for which no sentence is quoted: cancer (3 papers); laryngeal carcinoma (2); colon cancer (1); cyst (1); developmental delays (1); infection (1); Insulin resistance (1); tumor (1); Uterine leiomyoma (1).